IPO11 (importin 11)
Description:
Functions in nuclear protein import as nuclear transport receptor. Serves as receptor for nuclear localization signals (NLS) in cargo substrates. Is thought to mediate docking of the importin/substrate complex to the nuclear pore complex (NPC) through binding to nucleoporin and the complex is subsequently translocated through the pore by an energy requiring, Ran-dependent mechanism. At the nucleoplasmic side of the NPC, Ran binds to the importin, the importin/substrate complex dissociates and importin is re-exported from the nucleus to the cytoplasm where GTP hydrolysis releases Ran. The directionality of nuclear import is thought to be conferred by an asymmetric distribution of the GTP- and GDP-bound forms of Ran between the cytoplasm and nucleus (By similarity). Mediates the nuclear import of UBE2E3, and of RPL12 (By similarity).
Synonyms: RanBP11; IPO11-LRRC70
Tractability: PROTAC: ubiquitination databases record sites on it; its protein half-life has been measured.
Gene: Protein-coding gene on chromosome 5 (62,403,518 to 62,629,949, forward strand). Ensembl gene ENSG00000086200.
Subcellular location: Cytoplasm; Nucleus
Subcellular location (Human Protein Atlas): Nucleoplasm; Cytosol
Gene Ontology:
Molecular function: protein binding; nuclear import signal receptor activity; small GTPase binding
Biological process: import into nucleus; intracellular protein transport
Cellular component: cytosol; nucleoplasm; nuclear envelope; cytoplasm; nucleus
Genetic constraint (gnomAD): Loss-of-function variants: 25 observed, 58.4 expected, observed/expected ratio (o/e) 0.43, 90% interval 0.31 to 0.6. The upper end of that interval is the gene's LOEUF score, 0.6, which puts it in group 2 of 6, group 1 being the genes least tolerant of losing a copy. Missense variants: 509 observed, 575.54 expected, observed/expected ratio (o/e) 0.88, 90% interval 0.82 to 0.95. Synonymous variants: 206 observed, 202.94 expected, observed/expected ratio (o/e) 1.02, 90% interval 0.9 to 1.14.
Homologues: Orthologues: chimpanzee IPO11 (99% identical), macaque IPO11 (99% identical), pig IPO11 (98% identical), dog IPO11 (98% identical), mouse Ipo11 (97% identical), guinea pig IPO11 (96% identical), zebrafish ipo11 (83% identical), tropical clawed frog ipo11 (82% identical), rat Ipo11 (81% identical), Drosophila melanogaster Impbeta11 (37% identical). Paralogues in human: IPO9 (17% identical), IPO7 (16% identical), IPO8 (16% identical), CSE1L (15% identical).
Diseases named in the same sentence as IPO11 in open-access papers:
IPO11 is named in the same sentence as 12 diseases in open-access papers, as found by Europe PMC text mining. Sharing a sentence is not in itself a finding about the gene and the disease. The quoted sentences say what the papers report.
colorectal cancer (4 papers, 2020 to 2024). A primary or metastatic malignant neoplasm that affects the colon or rectum. "We report the modeling docking analysis of importin-11 homology model with five phyto compounds in the context of colorectal cancer for further consideration." (PMID 32405167, 2020).
colon cancer (3 papers, 2020 to 2024). "Therefore, it is of interest to design inhibitorsto the protein target importin-11, which transports β-catenin linked to colon cancer cells." (PMID 32405167, 2020). "Therefore,it is of interest to describe the design of inhibitors to the protein target importin-11 which transports β-catenin linked to colon cancer cells." (PMID 32405167, 2020). "Using a CRISPR-based screening platform, recent work provided evidence that β-catenin may be imported by the NTR, IPO11 (Importin-11); however, this mechanism appears curiously relevant only for a subset of colon cancer cells." (PMID 36300792, 2022). "Although it remains possible that IPO11 might ultimately have a role in β-catenin nuclear transport in some vertebrate cells, the current evidence suggests that it plays a critical role only in a subset of colon cancer cells." (PMID 36300792, 2022).
bladder tumors (1 paper, 2016). "The absolute copy numbers were determined by qPCR, which revealed that the IPO11 CNV rate was 64.0% (16/25) and that IPO11 copy number alterations were significantly associated with aberrant expression of IPO11 mRNA in the bladder tumors." (PMID 27689332, 2016).
Diabetes (1 paper, 2018). "A pharmacogenetic analysis using a genome‐wide approach in the ACCORD (Action to Control Cardiovascular Risk in Diabetes) trial identified HSD17B3, SMAD3, and IPO11 as genetic markers of fenofibrate response." (PMID 30371334, 2018).
leukemia (1 paper, 2022). A malignant (clonal) hematologic disorder, involving hematopoietic stem cells and characterized by the presence of primitive or atypical myeloid or lymphoid cells in the bone marrow and the blood. "In OCI-AML2, NB4, and TEX leukemic cells, knockdown of IPO11 reduced clonogenic growth, consistent with an effect on leukemia initiating cells." (PMID 35152270, 2022). "Of importance the expression of IPO11 is higher in LSCs compared to bulk leukemia cells." (PMID 35152270, 2022). "We also confirmed that partial target knockdown of IPO11 with shRNA reduced AML growth and viability of OCI-AML2, NB4 and TEX leukemia cells >80%." (PMID 35152270, 2022). "Through a comparison of genes that are significant for growth and viability of AML cells by way of a CRISPR screen, with genes that are differentially expressed in leukemia stem cells (LSC), we identified importin 11 (IPO11) as a novel target in AML." (PMID 35152270, 2022). "IPO11 was detected at the protein level only in the C34+ stem cell fraction, and not in the CD34− bulk leukemia fraction of 8227 cells." (PMID 35152270, 2022).
melanoma (1 paper, 2020). A malignant, usually aggressive tumor composed of atypical, neoplastic melanocytes. "In order to validate those predicted targets, we transfected four melanoma cell lines with mimics for either miR1290, miR-23a-5p or miR-23b-5p followed by expression analysis of FXR2 and IPO11 by qPCR and Western blot." (PMID 32183388, 2020).
parasitic infection (1 paper, 2023). "On the other hand, parasitic infection decreased sperm quality and downregulated the expression levels of Herc4, Ipo11, and Mrto4, and these genes were strongly related to spermatogenesis." (PMID 36982803, 2023). "In order to assess the relationship between parasitic infection and testicular spermatogenic function, we determined the gene expression levels of Herc4, Ipo11, and Mrto4 by qRT-PCR." (PMID 36982803, 2023).
prostate carcinoma (1 paper, 2020). A carcinoma that arises from epithelial cells of the prostate gland. "In prostate cancer cells lacking IPO11 function,PTEN was found to be much more cytoplasmic at stable state than control cells and in dynamic experiments IPO11 disturbance greatly slowed down entry of PTEN into the nucleus." (PMID 32405167, 2020).
Trichinella spiralis infection (1 paper, 2023). "Trichinella spiralis infection downregulated the gene expression levels of Herc4, Mrto4, and Ipo11, genes closely related to the production and functional expression of sperm, which led to the decrease in sperm count." (PMID 36982803, 2023). "Consistent with previous studies, Trichinella spiralis infection decreased the sperm quantity and quality, and the expression levels of genes related to spermatogenesis were also suppressed including Herc4, Ipo11, and Mrto4." (PMID 36982803, 2023).
cancer (6 papers, 2013 to 2026). A tumor composed of atypical neoplastic, often pleomorphic cells that invade other tissues. "This work must also be reconciled with a recent study that implicated IPO11 as an important factor for β-catenin nuclear transport in a subset of cancer cells." (PMID 36300792, 2022). "For instance, nine of our candidate cancer genes were also contained in the Cancer Gene Census list, which comprises 487 genes causally linked to cancer, representing a highly significant enrichment (Abl2, Braf, Fbxw7, Foxp1, Ipo11, Mllt3, Fas, Pten, and Nf1; p<0.0002, Fisher’s exact test)." (PMID 23940809, 2013). "How IPO11 contributes to β-catenin nuclear import in the context of specific cancer cell lines remains to be fully established." (PMID 36300792, 2022). "In an expanded sample of 114 BCa patients with follow-up data, those with importin-11 overexpression had worse overall survival (OS), cancer-specific survival (CSS) and cancer-free survival (CFS), as determined using a Kaplan-Meier analysis curve." (PMID 27689332, 2016). "Furthermore, inhibiting the activity of Importin-11 suppressed the growth of tumors formedby APC mutant cancer cells isolated from patients.There are many reports also showed that Importin-11 is one of main transport receptors andact as target for many cancer types." (PMID 32405167, 2020).
tumor (5 papers, 2016 to 2026). "Tumor progression may be caused by importin-11 overexpression through acceleration of the degradation of some tumor suppressors via the promotion of UbcM2 nuclear translocation." (PMID 27689332, 2016). "Protein profiling identified ITH-associated proteins (WDR5, CKB, IPO11, ATP6V1F, DCXR and PCCB) and underscored pathway variations including tumour suppressor and proto-oncogenic signalling, vascularization and metabolic regulation." (PMID 41580526, 2026). "Here we identified a conserved circRNA circIPO11 (originated from IPO11 gene transcript, circbase symbol hsa_circ_0007915) that is highly expressed in tumor tissues and liver CSCs." (PMID 34649567, 2021). "The function of IPO11 is controversial, which has been reported as a tumor suppressor." (PMID 34649567, 2021). "Hence, we further analyzed the absolute copy numbers and mRNA expression of IPO11 in additional tumor tissues from 25 BCa patients (a superficial tumor was used if the tumor was invasive) and matched normal mucosa by quantitative polymerase chain reaction (qPCR)." (PMID 27689332, 2016). "Importin-11 (IPO11) is a nuclear transport receptor for protein import and simultaneously serves as a proto-oncogene and a tumour suppressor gene." (PMID 41580526, 2026). "We performed whole-exome sequencing to analyze superficial tumor tissues (Tsup) and basal tumor tissues (Tbas) from 3 MIBC patients and identified previously unreported copy number variations in IPO11 that warrants further investigation as a molecular target." (PMID 27689332, 2016).
IPO11 also shares sentences with these, for which no sentence is quoted: bladder cancer (1 paper).